SPHK2 (sphingosine kinase 2)
Diseases named in the same sentence as SPHK2 in open-access papers (continued):
Sharing a sentence is not in itself a finding about the gene and the disease.
atherosclerosis (10 papers, 2019 to 2025). A disease characterized by the build-up of fatty material and calcium deposition in the arterial wall resulting in partial or complete occlusion of the arterial lumen. "Macrophages from SphK2-knockout mice showed an increase in ceramide levels, while SphK1 overexpression in SphK2-deficient mice reduced ceramide levels, thereby ameliorating atherosclerosis." (PMID 35409370, 2022). "Transgenic overexpression of SphK1 in SphK2-deficient mice rescued aggravation of atherosclerosis and abnormalities of autophagosomes and lysosomes in macrophages with reductions of sphingosine, suggesting at least partial overlapping actions of two SphKs." (PMID 31797978, 2019). "Sphk1 overexpression in Sphk2-deficient mice rescues aggravated atherosclerosis." (PMID 39899071, 2025). "SphK2 is required for autophagosome and lysosome-mediated intracellular lipid droplet breakdown to impede the development of atherosclerosis." (PMID 36547431, 2022). "Sphingosine kinase 2 (SPHK2) is also required for the autophagy-mediated catabolism of intracellular LDs to prevent the development of atherosclerosis by reducing sphingosine content in macrophages." (PMID 32582708, 2020). "Further studies including analysis of macrophage-specific Sphk2 KO mice are required for fully understanding a role of SphK2 in atherosclerosis." (PMID 31797978, 2019). "Further studies using both male and female mice are required to reveal the possible effects of sex difference on the role of SphK2 in atherosclerosis." (PMID 31797978, 2019). "In the present study, the effects of genetic deletion of Sphk2 and Sphk1 on atherosclerosis were clearly different." (PMID 31797978, 2019). "Total intimal lesion size and ORO-positive area in the cross-sections of the aortic sinus, a site frequently affected by atherosclerosis, were greater in Sphk2−/− mice than control mice." (PMID 31797978, 2019). "SphK1 and SphK2 have distinct, isoform-specific roles in atherosclerosis." (PMID 39920588, 2025). "Moreover, the authors found that SPHK2 is responsible for autophagosome- and lysosome-mediated catabolism of the intracellular lipids, therefore SPHK2 has been suggested to be a novel target for the treatment of atherosclerosis." (PMID 36119733, 2022). "However, it is possible that SphK1 and SphK2 have distinct, isoform-specific roles in atherosclerosis." (PMID 31797978, 2019). "Consistent with this notion, we observed enhancement of lipopolysaccharide-induced IL-1β release in SphK2−/− mice, which may contribute to aggravation of atherosclerosis." (PMID 31797978, 2019). "Taken together, these results indicate that SphK2 is required for autophagosome- and lysosome-mediated catabolism of intracellular lipid droplets to impede the development of atherosclerosis; therefore, SphK2 may be a novel target for treating atherosclerosis." (PMID 31797978, 2019). "In Western diet (WD)-fed Sphk1−/− mice and Sphk2−/− mice, both with an ApoE-deficient background, the exacerbation of atherosclerosis in mice lacking Sphk2, but not Sphk1, was attributed to impaired autophagic degradation of lipid droplets (LDs) in macrophages." (PMID 39920588, 2025). "Nonetheless, aggravated atherosclerosis is observed in Sphk2- and not Sphk1-deficient mice." (PMID 39899071, 2025). "We assessed whether SphK1 overexpression can rescue atherosclerosis in Sphk2−/− mice." (PMID 31797978, 2019). "In this study, we analysed atherosclerosis in Western diet (WD)-fed Sphk1−/− mice and Sphk2−/− mice, both with an ApoE-deficient background and found that Sphk2−/− mice, but not Sphk1−/− mice, show aggravation of atherosclerosis because of defective autophagic breakdown of LDs in macrophages." (PMID 31797978, 2019). "Researchers have speculated that BC294640 targets SphK1 and SphK2 at different concentrations; nonetheless, it is possible that both isoforms were not equally suppressed during treatment, thereby explaining the bidirectional regulatory effect of SphKs on atherosclerosis." (PMID 39920588, 2025).
atherosclerosis (continued). "Genetic disruption of SphK2 in mouse models has been reported to exacerbate atherosclerosis, thus epigenetic regulation of ABCA1 and LXR target genes by SphK2 may be the key to understanding the anti-atherogenic mechanism of FTY720." (PMID 36498944, 2022). "Taken together, FTY720 induces ABCA1 expression through SphK2-mediated acetylation of H3K9 and suppresses lipid accumulation in macrophages, which provides novel insights into the mechanisms of action of FTY720 on atherosclerosis." (PMID 36498944, 2022). "Some discrepant findings were observed in atherosclerosis development where SPHK2 inhibition by ABC294640 induces complex alterations and ultimately does not affect atherosclerosis." (PMID 39899071, 2025).
Obesity (10 papers, 2013 to 2023). Accumulation of substantial excess body fat. "They characterized metabolic parameters of SphK2 KO old mice compared to control old mice, as aging is associated with weight gain and obesity." (PMID 32849282, 2020). "In white adipose tissue, SphK1 prevents obesity-associated diabetes, whereas the adipose-specific role of SphK2 remains elusive." (PMID 33633691, 2020). "Overall, these data indicated that inhibition of SphK2 could be an attractive target to develop treatments to ameliorate insulin resistance but also insulin secretion associated with obesity and T2D." (PMID 32849282, 2020). "Sphingosine kinase 2 mutant flies were fed with a regular diet (referred to as Sk2 flies) representing the genetic-induced obesity model." (PMID 36810287, 2023). "It was indicated in one study that plasma S1P is elevated in obesity, and sphingosine kinase 2 knockout mice were protected from obesity and insulin resistance." (PMID 35266264, 2022). "Nevertheless, this study indicates that SphK2 may be a negative regulator of glucose homeostasis in an obesity context." (PMID 32849282, 2020).
colorectal cancer (9 papers, 2015 to 2023). A primary or metastatic malignant neoplasm that affects the colon or rectum. "ABC294640, a SphK2 specific inhibitor, also induced ceramide production and Akt-mTOR inactivation, thereby inhibiting colorectal cancer cell growth in vitro and in vivo." (PMID 37604912, 2023). "The positive correlation between SphK2 and S1P also existed in murine adenocarcinoma cells and colorectal cancer cells." (PMID 33968977, 2021). "Additionally, miR-363-3p took part in the inhibition of tumor growth and metastasis in colorectal cancer by SphK2." (PMID 33432525, 2021). "Importantly, down-regulation of both S1P-producing enzymes SphK1 and SphK2 by siRNA reduced the formation of focal adhesions in primary colorectal cancer cells, which was accompanied by suppression of FAK activity." (PMID 32456134, 2020). "In addition, a significant correlation between the expression of FASN and SphK2 at mRNA and protein level was detected in primary colorectal cancer." (PMID 32456134, 2020).
diabetes (9 papers, 2020 to 2025). "We have recently reported that global deletion of either Sphk1 or Sphk2 exhibited a significant impact on diabetes in the animal models, i.e., loss of Sphk1 promotes, but Sphk2 deficiency protects, the disease." (PMID 34530846, 2021). "In contrast, SphK2 can be pathogenic, as systemic loss of Sphk2 ameliorates diabetes by preventing pancreatic β-cell death and improves insulin sensitivity in aged mice by promoting lipolysis in adipose tissue." (PMID 32917816, 2020). "For instance, we have recently reported that global deletion of Sphk1 in mice resulted in a significant loss of pancreatic β-cell mass and promoted the onset of diabetes, whereas Sphk2 deficiency ameliorated diabetic phenotype by protecting β-cells against lipoapoptosis." (PMID 34530846, 2021). "Indeed, in recent years, an increasing body of evidence has suggested an important role of SphK2 in both insulin resistance and pancreatic β-cell dysfunction, the two key pathogenic factors of diabetes." (PMID 34530846, 2021). "The finding that dhS1P and dhS1P/dhSph ratio are elevated in serum up to 5 years before diabetes onset suggests that SphK2 activity could be stably associated with T2DM predisposition." (PMID 34530846, 2021). "More recently, we found that hepatocyte-specific Sphk2-deficent mice exhibited evident insulin resistance and pre-diabetes." (PMID 34530846, 2021). "So far, only hepatocyte-specific Sphk2-/- and adipocyte-specific Sphk1-/- have been applied in diabetes research." (PMID 33633691, 2020). "Taken together, our findings that SphK1 protects but SphK2 promotes β-cell lipotoxicity suggest a new strategy by balancing between the signaling of SphK1 and SphK2 in β-cells for the prevention and treatment of diabetes." (PMID 33633691, 2020). "Restoration of SphK2 expression and pharmacological depletion of sphingosine levels substantially improved hepatic insulin sensitivity, which provides a potential therapeutic option against diabetes." (PMID 32917816, 2020). "Although we are currently unable to assess the contribution of these different functions of SphK2 to the overall metabolic homeostasis, the association of circulating dhS1P/dhSph ratio with T2DM incidence has shed light on an important role of SphK2 in diabetes in a clinically relevant setting." (PMID 34530846, 2021). "SIP, a potential biomarker in many diseases, including diabetes, is synthesized from sphingosine by two sphingosine kinases: SPHK1 and SPHK2." (PMID 41301404, 2025). "Despite increased sphingoid-1-phosphate levels in diabetic pregnancies with preeclampsia, no changes were seen in placental SPHK1 or SPHK2 enzyme levels in either diabetes type in the presence of preeclampsia." (PMID 36979912, 2023).
prostate carcinoma (9 papers, 2016 to 2026). A carcinoma that arises from epithelial cells of the prostate gland. "GO group 3 contains genes with roles in sphingolipid metabolism including SPHK2, which has been shown to promote prostate cancer." (PMID 41540805, 2026). "As demonstrated, the mRNA expression of both SphK1 and SphK2 was significantly elevated in human prostate cancer tissues (“T”) from 10 different CRPC patients (tissues were provided by Dr. Mi)." (PMID 37604912, 2023). "Since SKI-178 can block both SphK1 and SphK2, it was not surprising to show that SKI-178-induced SphK inhibition and prostate cancer cell death were significantly more potent than the SphK1 inhibitor PF-543 and the SphK2 inhibitor ABC294640." (PMID 37604912, 2023). "Sphingosine kinases (SphK), including SphK1 and SphK2, are important enzymes promoting progression of prostate cancer." (PMID 37604912, 2023). "Bioinformatics analyses and results from local tissues demonstrated that that both SphK1 and SphK2 are upregulated in human prostate cancer tissues." (PMID 37604912, 2023). "Contrarily, ectopic overexpression of SphK1 and SphK2, by lentiviral constructs, further increased promoted primary prostate cancer cell growth in vitro and in vivo." (PMID 37604912, 2023). "The protein expression of both SphK1 and SphK2 was upregulated in prostate cancer tissues of three representative patients (“Patient-1/-2/-3”)." (PMID 37604912, 2023). "The lentiviral SphK1-overexpressing construct and the lentiviral SphK2-overexpressing construct were co-transduced to pCan1 primary prostate cancer cells, and stable cells were established after selection: “oe-SphK1+oe-SphK2” pCan1 cells." (PMID 37604912, 2023). "When combining all 10 sets of tissue blotting data, we found that SphK1 and SphK2 protein upregulation was significant in the local prostate cancer tissues." (PMID 37604912, 2023). "Here the TCGA database results and results from local tissues demonstrated that that both SphK1 and SphK2 are upregulated in human prostate cancer tissues." (PMID 37604912, 2023). "Ectopic overexpression of SphK1 and SphK2, by lentiviral constructs, promoted primary prostate cancer cell proliferation and migration." (PMID 37604912, 2023). "Moreover, upregulation of SphK2 transcripts was detected in the prostate cancer tissues from the TCGA database." (PMID 37604912, 2023). "Interestingly, ectopic overexpression of SphK1 and SphK2 further increased Akt-mTOR activation in primary prostate cancer cells." (PMID 37604912, 2023). "In addition, the treatment of early stage and advanced prostate cancer cells with the selective SPHK2 inhibitor, ABC294640, induces a reduction in Myc and androgen receptor (AR) expression, and this is associated with significant inhibition of growth, proliferation, and cell cycle progression." (PMID 32260399, 2020). "We also compared the anti-prostate cancer cell activity between SKI-178 and other SphK1/2 inhibitors, including the SphK1 inhibitor PF-543 and the SphK2 inhibitor ABC294640." (PMID 37604912, 2023). "SphK2 is also a well-established anticancer target, with the SphK2 inhibitor opaganib (ABC294640, Ki = 9.8 μM) successfully reaching phase 2 clinical trials for prostate cancer." (PMID 40006080, 2025). "Moreover, SphK2 inhibition by ABC294640 inhibited viability and proliferation in androgen resistant prostate cancer cells." (PMID 37604912, 2023). "The inhibitor of the SphK1 and SphK2 isozymes, SKi (2-(p-hydroxyanilino)-4-(p-chlorophenyl) thiazole)) induced proteosomal degradation of hSphK1a and hSphK1b in androgen-sensitive prostate cancer cells, however failed to promote degradation of hSphK1b in androgen-independent prostate cancer cells." (PMID 28415564, 2017).
glioblastoma (8 papers, 2012 to 2023). The most malignant astrocytic tumor (WHO grade IV). "In contrast, SPHK2 was highly expressed in glioblastoma cell lines (GSC827 and GSC923) while it was undetectable in both IDH1mut cell lines." (PMID 33050528, 2020). "Furthermore, we found that, co-cultured with glioblastoma cells, GECs exhibit increased SphK2 expression and activity, with a significant S1P secretion enhancement." (PMID 35326565, 2022). "Moreover, selective inhibition of SphK1 or SphK2 with siRNA in U-1242 and U-87MG glioblastoma cell lines showed an inhibition of cell proliferation, with more potent action when SphK2 was silenced." (PMID 34357010, 2021). "Interestingly, knockdown of SphK2 presented more potent inhibition of glioblastoma cell proliferation than SphK1 knockdown." (PMID 34305532, 2021).
leukemia (8 papers, 2013 to 2023). A malignant (clonal) hematologic disorder, involving hematopoietic stem cells and characterized by the presence of primitive or atypical myeloid or lymphoid cells in the bone marrow and the blood. "In vitro studies using human leukemia U937 cells demonstrated that K145 accumulates in U937 cells, suppresses the S1P level, and inhibits SphK2." (PMID 23437140, 2013). "Another specific SphK2 inhibitor, K145 (3-(2-amino-ethyl)-5-[3-(4-butoxyl-phenyl)-propylidene]-thiazolidine-2,4-dione)), reduced S1P levels in leukemia cells and demonstrated growth inhibitory and apoptotic effects in murine models." (PMID 24970177, 2013). "Furthermore, knockout of the Sphk2 gene reduces leukemia development in a mouse model of acute lymphoblastic leukemia (ALL), and pharmacologic inhibition extends survival of mice in xenograft models of human disease." (PMID 32260399, 2020). "The similar latency and features of the disease in MAR and MARS2 mice suggests that the principal effect of SphK2 loss was on leukemia initiation rather than rate of disease progression." (PMID 29441205, 2018). "In addition, recent evidence shows SphK2 may play a critical role in regulating cell proliferation and apoptosis in other types of cancer, i.e., mammary adenocarcinoma, hepatocellular carcinoma, leukemia." (PMID 24970177, 2013).
lung carcinoma (8 papers, 2017 to 2025). "The level of SphK2 is up-regulated in the oncogenic environment, and SphK2 mRNA is up-regulated in colon and lung cancer cells." (PMID 38419070, 2024). "We found that RPTOR promoted the cerebral invasion of the NSCLC lung cancer cells by the SPHK2/S1P/STAT3 axis." (PMID 38163890, 2024). "Knocking down or inhibiting SphK2 inhibited growth of lung cancer cells in vitro and in mouse xenograft models." (PMID 34069611, 2021). "Results of western blot indicated that protein expression level of SphK2 in human lung cancer cell lines H460, H1299, A549, SPC-A-1, Calu-3 was much higher than that in NHBE, and more obvious in H1299 and A549 cell lines." (PMID 28428733, 2017). "Similarly, Sphk2 was also found to be highly expressed in lung cancer and correlated with lower overall survival when compared to patients that exhibited low levels of Sphk2." (PMID 34071409, 2021). "Therefore, we hypothesized that RPTOR may promote the brain metastasis of lung cancer through the SPHK2/S1P/STAT3 axis." (PMID 38163890, 2024). "The SPHK2 inhibitor, ABC294640, also reversed the RPTOR overexpression-increased migration and invasion of lung cancer cell lines and the permeability of BBB models." (PMID 38163890, 2024). "Studies show that the up-regulation of SPHK2 is associated with growth and metastasis in various cancers and that the overexpression of SPHK2 can inhibit the cellular apoptosis of NSCLC, suggesting that the activity of SPHK2 is related to the development and prognosis of lung cancer." (PMID 38163890, 2024). "Compared to the SPHK2 inhibitor Opaganib, which only reduces the release of IL-6 from PBMC of lung cancer origin, inhibition of SPHK1 by PF543 can down-regulate both TNF-α and IL-6 release and more effectively inhibit lung cancer progression." (PMID 36823149, 2023). "FTY720 (Fingolimod/Gilenya, Novartis, Basel, Switzerland) is a sphingosine analogue drug that is phosphorylated by SphK2 to produce a structural analogue of S1P and functional antagonist for S1PR1 that acts a tumor suppressor in colon and lung cancer cell lines and mouse models." (PMID 34069611, 2021). "The addition of the SPHK2 inhibitor, ABC294640, to the RPTOR-overexpressed PC9 cells significantly inhibited the RPTOR-induced activation of the SPHK2/S1P/STAT3 signaling pathway and restrained the RPTOR overexpression-enhanced proliferation, migration and invasion of lung cancer cell lines." (PMID 38163890, 2024). "However, an effective use of FTY720 for cancer therapy would be to combine it with a SPHK2 inhibitor in order to prevent the synthesis of p-FTY720, which does not seem to play a role in chronic myeloid leukemia or lung cancer cell deaths and also causes immune suppression." (PMID 35565311, 2022).
acute lymphoblastic leukemia (7 papers, 2016 to 2022). Leukemia with an acute onset, characterized by the presence of lymphoblasts in the bone marrow and the peripheral blood. "We have previously demonstrated a role for SphK2 in the development of acute lymphoblastic leukemia (ALL)." (PMID 29441205, 2018). "Sphk2 has also been shown to have an oncogenic role in acute lymphoblastic leukemia by enhancing MYC expression." (PMID 26956050, 2016). "SphK2 is important for MYC expression to promote acute lymphoblastic leukemia progression." (PMID 29285269, 2017). "We have recently shown that chemical inhibition of SphK2 can reduce acute lymphoblastic leukemia (ALL) cell growth, induce cell death in vitro and extend the survival of mice bearing human ALL xenografts." (PMID 29441205, 2018). "The combination of vincristine and SPHK2 inhibitor ABC294640 significantly enhanced the inhibition of SPHK2 and further inhibited the survival and proliferation of T-cell acute lymphoblastic leukemia (T-ALL) cells." (PMID 35965565, 2022).